EFHC2 (EF-hand domain containing 2)
Description:
Microtubule inner protein (MIP) part of the dynein-decorated doublet microtubules (DMTs) in cilia axoneme, which is required for motile cilia beating.
Synonyms: FLJ22843; MRX74; dJ1158H2.1
Tractability: Small molecule: a structure with a bound ligand is known.
Gene: Protein-coding gene on chromosome X (44,146,255 to 44,343,850, reverse strand). Ensembl gene ENSG00000183690.
Subcellular location: Cytoplasm, cytoskeleton, cilium axoneme; Cytoplasm, cytoskeleton, flagellum axoneme
Gene Ontology:
Molecular function: protein binding; calcium ion binding
Biological process: flagellated sperm motility; regulation of dendrite morphogenesis
Cellular component: axonemal microtubule; ciliary basal body; axonemal A tubule inner sheath; sperm flagellum; axoneme
Homologues: Orthologues: chimpanzee EFHC2 (99% identical), macaque EFHC2 (96% identical), pig EFHC2 (77% identical), rat Efhc2 (75% identical), mouse Efhc2 (74% identical), rabbit EFHC2 (72% identical), dog EFHC2 (71% identical), guinea pig EFHC2 (68% identical), tropical clawed frog efhc2 (53% identical), zebrafish efhc2 (53% identical), Drosophila melanogaster Efhc1.1 (33% identical), Drosophila melanogaster Efhc1.2 (33% identical). Paralogues in human: EFHC1 (31% identical), EFHB (14% identical).
Diseases named in the same sentence as EFHC2 in open-access papers:
EFHC2 is named in the same sentence as 21 diseases in open-access papers, as found by Europe PMC text mining. Sharing a sentence is not in itself a finding about the gene and the disease. The quoted sentences say what the papers report.
juvenile myoclonic epilepsy (2 papers, 2015 to 2018). "EFHC2 has been implicated in several brain-related genetic diseases like Turner syndrome and juvenile myoclonic epilepsy." (PMID 30349665, 2018). "EFHC2 has also been associated with harm avoidance, learning disability and juvenile myoclonic epilepsy." (PMID 26107779, 2015).
Turner syndrome (2 papers, 2015 to 2018). Turner syndrome is a chromosomal disorder associated with the complete or partial absence of an X chromosome. "Previous studies of X-monosomic women with Turner syndrome suggest a genetic association with facial fear recognition abilities at Xp11.3, specifically at a single nucleotide polymorphism (SNP rs7055196) within the EFHC2 gene." (PMID 26107779, 2015).
congenital blindness (1 paper, 2022). "The contiguous deletion containing EFHC2 gene results in congenital blindness, and REV3L was one of candidate genes who can impair the activity of abducens nerves that endow eyes the ability of looking to the side." (PMID 35456484, 2022).
epilepsy (1 paper, 2007). A brain disorder characterized by episodes of abnormally increased neuronal discharge resulting in transient episodes of sensory or motor neurological dysfunction, or psychic dysfunction. "In this case, epilepsy, not a common trait of Norrie disease, is probably caused by the deletion of the EFHC2 gene." (PMID 18047645, 2007).
EFHC2 also shares sentences with these, for which no sentence is quoted: asthenozoospermia (1 paper); chronic fatigue syndrome (1); cutaneous T-cell lymphoma (1); dysplasia (1); generalized epilepsy (1); genetic diseases (1); Hydrocephalus (1); male infertility (1); microcephaly (1); Norrie disease (1); osteopetrosis (1); panic disorder (1); personality disorder (1); Pseudoxanthoma elasticum (1); renal failure (1); Sezary syndrome (1); tumor (1).